SIRT5 (sirtuin 5)
Diseases named in the same sentence as SIRT5 in open-access papers (continued):
Sharing a sentence is not in itself a finding about the gene and the disease.
tumor (continued). "Therefore, SIRT4 and SIRT5 potentially inhibit the occurrence and development of ccRCC, whereas high expression of SIRT3, SIRT6, and SIRT7 might have an important tumor-promoting role." (PMID 37096064, 2023). "Combined with SIRT expression (mRNA and protein) and the prognostic value of SIRTs (mentioned previously herein), we speculate that SIRT4 and SIRT5 might be possible tumor suppressor markers, whereas SIRT6 and SIRT7 could play an important role in promoting tumor development." (PMID 37096064, 2023). "In short, similar to SIRT4 and SIRT5, SIRT6 might have a tumor suppressor function in GC." (PMID 36358890, 2022). "Interestingly, 5-FU treatment significantly decreased tumor growth and weight in the control vector and SIRT5 H158Y groups, but this effect was not notable in the SIRT5 WT group." (PMID 36253417, 2022). "Herein our data indicated that SIRT5 silencing increased the lysine malonylation levels of TKT, thereby suppressing the non-oxidative PPP and leading to insufficient R5P levels for nucleotide synthesis, which contributed to DNA damage and growth inhibition of tumor cells." (PMID 36253417, 2022). "Expression of SIRT5 was absent in normal prostate tissues but high in tumour tissues." (PMID 33103371, 2020). "Given the metabolic plasticity of PDAC, SIRT5’s role in regulating noncanonical metabolic pathways positions it as a promising therapeutic target, with its activation offering a potential strategy to suppress tumor growth and improve the efficacy of existing treatments." (PMID 39682281, 2024). "Therefore, it remains unclear whether SIRT5 may play an important role under other physiological or pathological conditions, such as long time HFD, fasting, hypoxia, low glucose, low glutamine, or the tumor microenvironment." (PMID 34966740, 2021). "The results suggest the two-edged nature of sirtuins: whereas certain isoforms (e.g., SIRT5) defend malignant cells, thereby undermining therapy, others, such as SIRT2, are involved in tissue-specific protection without promoting tumor survival." (PMID 41425553, 2025). "This study shows that, similar to SIRT4 and SIRT5, SIRT6 expression is lower in GC tissue when compared to normal gastric tissue, and that its decreased expression correlates with tumor grade, tumor size, and TNM stage, along with decreased overall survival and DFS of GC patients." (PMID 36358890, 2022). "Therefore, we propose that inhibiting SIRT5’s desuccination activity on PPA2 could specifically target HIF-1α for ubiquitination and degradation in tumor cells without affecting normal cells." (PMID 40164945, 2025). "However, there has not yet been any final verdict reached on whether SIRT5 has a positive or negative role in HCC, although it is expressed at only low levels in tumour specimens." (PMID 32596968, 2020). "However, there has been no final verdict as to whether SIRT5 has a positive or negative role in HCC, although it has a relatively low‐expression level in tumour specimens in different databases (data not shown)." (PMID 32596968, 2020).
cancer (98 papers, 2015 to 2025). A tumor composed of atypical neoplastic, often pleomorphic cells that invade other tissues. "SIRT5 plays a pivotal role in cellular energy metabolism and homeostasis, with its dysregulation being implicated in various types of cancer." (PMID 39944690, 2025). "Although SIRT5 has been implicated in various pathways, its specific interactions and regulatory networks within different cancer types remain inadequately defined." (PMID 39944690, 2025). "In cell culture and animal models, the loss of SIRT5 has been shown to impair cancer cell proliferation." (PMID 41107644, 2025). "The integration of multi-disciplinary approaches, including systems biology, computational modeling, and translational research, will be crucial for overcoming the complexities associated with SIRT5’s multifaceted roles in cancer." (PMID 39944690, 2025). "The need for effective modulators of SIRT5 is increasing as more and more studies associate SIRT5 with a range of diseases, particularly cancer." (PMID 39979670, 2025). "By contrast, associations of stronger upregulation of SIRT1, SIRT2, and SIRT5 with sensitivity to dasatinib were unexpected, since previous studies had reported benefits of their downregulation or depletion in improving cancer outcomes." (PMID 38369747, 2024). "Studies using syngenic and xenograft mouse models of AML have shown that overexpression of SIRT5 causes tumorigenesis and cancer growth." (PMID 36980194, 2023). "Here, we will examine the current knowledge about the structure and catalytic mechanism of SIRT5 and we will delve into its main targets and the biological, metabolic, and cancer-related functions associated with its dysregulation." (PMID 36980194, 2023). "Recent studies have shown that SIRT5 is associated with cancer progression through the regulation of succinylation of specific proteins involved in cancer progression." (PMID 35278714, 2023). "Taken together, these studies suggest that SIRT5 has a context-dependent role in each mutation-specific cancer subtype." (PMID 36980194, 2023). "Many cancer cells increase Sirt5 expression; however, the underlying mechanism has remained elusive." (PMID 35963851, 2022). "Altered activities of SIRT5’s targets, such as pyruvate dehydrogenase complex and succinate dehydrogenase, are both implicated in cancer cell metabolic dysregulation." (PMID 29416026, 2018). "Its involvement in these pathways suggests that dysregulation of SIRT5 is associated with to the progression of several diseases, such as metabolic disorders, cardiovascular and neurodegenerative conditions, infectious diseases, and cancer." (PMID 40799515, 2025). "Research indicates that succinyltransferases and de-succinylases promote or inhibit the progression of various cancers by regulating the succinylation levels of substrate targets.SIRT5, the only known mitochondrial desuccinylase, is associated with metabolic disorders and cancer." (PMID 40557149, 2025). "The roles played by SIRT5 in different pathways imply that its dysregulation is associated with the development of different diseases, including metabolic disorders, cardiovascular and neurodegenerative pathologies, infectious diseases, and cancer." (PMID 36980194, 2023). "The development of specific SIRT5 regulators has emerged as a promising approach in clinical cancer therapy." (PMID 39944690, 2025). "Further studies revealed that Sirt5 plays an important role in supporting cancer cell metabolism by regulating various enzyme activities and protecting glutaminase C (GAC), an enzyme essential for glutamine catabolism, from degradation." (PMID 40598593, 2025). "A recent study reported that SIRT5 desuccinylates malic enzyme 2, thus facilitating mitochondrial respiration and cancer growth in CRC." (PMID 40164945, 2025). "Contextual dependency defines their activity: SIRT1 and SIRT5, for example, suppress or stimulate glycolysis based on the cancer type and metabolic stress." (PMID 41425553, 2025).
cancer (continued). "Addressing these issues will not only enhance our understanding of SIRT5’s biological functions but also pave the way for innovative cancer therapies targeting this enzyme." (PMID 39944690, 2025). "More direct evidence of malonylation aiding tumors comes from the flipside of the SIRT5 studies: cancer cells actively exploit SIRT5 to remove malonylation, implying that if malonylation is left unchecked, it would harm them." (PMID 41107644, 2025). "Essentially, forcing cancer cells to experience hypermalonylation (either by SIRT5 inhibition or malonyl-CoA accumulation) can tip their finely tuned metabolism into dysfunction, leading to growth arrest or cell death." (PMID 41107644, 2025). "As our understanding of SIRT5 functions deepens, its potential as a therapeutic target for cancer treatment becomes increasingly evident." (PMID 39944690, 2025). "In summary, the research surrounding SIRT5 and its desuccinylation activity underscores its pivotal role in cancer biology." (PMID 39944690, 2025). "The acetylation-dependent control of vimentin by SIRT5 underlies its inhibitory role in EMT and motility in cancer cells." (PMID 41304967, 2025). "In line with this, SIRT5 knockdown determined ROS level reduction and the hyperproliferation of cancer cells." (PMID 39215785, 2025). "On the other hand, SDH hyper-succinylation and reactivation result from suppressing SIRT5, which suppresses the proliferation of cancer cells." (PMID 40581650, 2025). "SIRT5 is frequently overexpressed in cancers, presumably to eliminate growth-inhibitory acylations (such as Kmal and Ksucc) and keep metabolism hot." (PMID 41107644, 2025). "The ongoing development of small molecule inhibitors or activators of SIRT5 offers new strategies for future cancer treatments." (PMID 39944690, 2025). "Sirtuin 5 (SIRT5) has emerged as a promising target for cancer therapy, though it exhibits dual roles in different cancer types." (PMID 40195331, 2025). "They showed that treatment with 5g reduced PDAC cancer cell viability (IC50s = 25.4–236.9 μM) and promoted protein deacetylation, analogously to SIRT5 overexpression." (PMID 39215785, 2025). "Studies have demonstrated that the succinylation of superoxide dismutase 1 (SOD1) promotes cancer cell proliferation; however, SIRT5 can reverse this effect by mediating desuccinylation and thereby restoring SOD1 enzyme activity." (PMID 39944690, 2025). "The investigation into SIRT5-mediated desuccinylation activity is still in its infancy, and the relationships and mechanisms between SIRT5 and multiple cancers require further exploration to provide guidance for future cancer treatments." (PMID 39944690, 2025). "Conversely, SIRT5-driven activation of the Nrf2/HO-1 axis enhances DNA repair and antioxidant defense in cancer cells, hence conferring drug resistance." (PMID 41425553, 2025). "Previous studies have demonstrated that SIRT5 not only enhances autophagy but also acts as a proliferative factor in several cancers, including colorectal, gastric, and breast cancers, as well as osteosarcoma." (PMID 40344161, 2025). "Despite the promising role of SIRT5 in cancer therapy, several challenges and future research directions must be addressed." (PMID 39944690, 2025). "Comparative analysis of the mitochondrial pathway gene expression revealed 11 pathways that were significantly different between high- and low-SIRT5-expression cancer cells." (PMID 39201811, 2024). "The study also confirmed the prognostic relevance of SIRT5 in other types of cancer, suggesting its potential applicability across various cancer types." (PMID 39110260, 2024). "SIRT5’s regulation of metabolic enzymes further adds another layer of complexity to cancer metabolism." (PMID 39682281, 2024). "The primary mechanism by which SIRT5 exerts its anti-cancer effect is through the regulation of metabolic processes." (PMID 39479446, 2024).
cancer (continued). "Assessment of the prognostic impact of SIRT5 in these 10 cancers revealed a correlation between SIRT5 expression levels and prognosis in COAD, KIRC, KIRP, READ, and UCEC, indicating the significant role of SIRT5 in cancers beyond COAD." (PMID 39110260, 2024). "The cell permeability of these peptide-based SIRT5 inhibitors is limited, constraining their use as selective chemical tools for studying SIRT5's biological functions in various diseases, particularly cancer." (PMID 38773972, 2024). "Emerging evidence also demonstrates the crucial role of SIRT5-mediated lysine desuccinylation in modulating cancer immunity." (PMID 39201811, 2024). "Mitochondrial sirtuins, especially SIRT3, SIRT4, and SIRT5, emerge as key regulators of cancer metabolism." (PMID 38331199, 2024). "SIRT5 has gained attention in cancer biology due to its involvement in multiple metabolic processes, yet its role in PCa remains insufficiently elucidated." (PMID 39796040, 2024). "SIRT5 also plays a role in modulating glutamine metabolism, potentially influencing cancer progression." (PMID 38773972, 2024). "Accordingly, we have summarized about 21 small-molecule compounds targeting SIRT3 and 3 small-molecule compounds targeting SIRT5 for the current cancer therapy." (PMID 38773972, 2024). "GO enrichment analysis revealed that genes enriched in high-SIRT5 cancer cells were involved in the regulation of cell growth and membrane organization." (PMID 39201811, 2024). "SIRT5 modulates metabolic pathways through protein modification, influencing cancer cell metabolism and survival." (PMID 38331199, 2024). "In this context, the E2F1 transcription factor, which controls the cell cycle by promoting cell proliferation, is positively regulated by SIRT5, thereby facilitating cancer cell proliferation and invasion." (PMID 36980194, 2023). "In order to unravel the role of GAC in cancer cells and to evaluate the role of the SIRT5/GAC/autophagy and mitophagy axis, GAC expression was silenced by transfecting MDA-MB-231 and CAL-62 with an shRNA plasmid." (PMID 37627630, 2023). "In the next paragraphs, we will also discuss its oncosuppressor role in some of the cancer types mentioned in the previous section, which emphasizes that the functional role of SIRT5 varies depending on both the tissue type and the specific setting." (PMID 36980194, 2023). "In HCT116 cells, LDHB K329 deacetylation performed by SIRT5 supported cell respiration and ATP synthesis, thereby promoting the growth of cancer cells also through this pathway." (PMID 36980194, 2023). "In cancer studies, SIRT5 was found to be downregulated in gastric cancer tissues and it enhanced autophagy via the AMP-activated protein kinase-mTOR signaling pathway." (PMID 36993975, 2023). "And data analysis based on scoring immunohistochemistry showed that aberrant expression of SIRT5 in ccRCC was closely related with pathological grading and cancer size with significant statistically difference (p < 0.05) according to Univariate analysis." (PMID 37096064, 2023). "Like other sirtuins, the activity of SIRT5 appears to be influenced by the molecular and biochemical conditions of the cancer." (PMID 37175631, 2023). "As a promoter of cancer development, SIRT5 can activate the expression of NRF2 and its related targets, which aid in protecting against oxidative stress and xenobiotics." (PMID 37175631, 2023). "SIRT5 is regarded as a potential therapeutic target for the treatment of different pathologies, including cancer, metabolic disorders, cardiovascular, and neurodegenerative diseases." (PMID 36980194, 2023). "By binding and succinylating pyruvate kinase M2 (PKM2), SIRT5 inhibits its activity, resulting in the buildup of glycolytic intermediates and promoting cancer growth." (PMID 37175631, 2023).
cancer (continued). "In comparison with the control vector and SIRT5 H158Y groups, cell inhibition rate analysis showed that cancer cells overexpressing SIRT5 WT demonstrated a significantly higher survival rate on 5-FU treatment." (PMID 36253417, 2022). "The authors further demonstrated that SIRT5 knockout cancer cells had increased levels of ROS and reduced levels of important antioxidants NADPH and GSH." (PMID 36291902, 2022). "Considering that SIRT5 promotes cancer cell survival and proliferation in a context-specific manner, its role in the metabolic reprogramming of tumors needs to be comprehensively explored." (PMID 36253417, 2022). "As for the other sirtuins, SIRT-5 also has a controversial role in cancer, being proposed as an oncogene in some cancers and as an oncosuppressor in others." (PMID 36080416, 2022). "Another study conducted on SGC-7901 and MGC-803 cancer cell lines with SIRT5 overexpression showed that SIRT5 inhibits GC cell proliferation, the ability to form colonies, and aerobic glycolysis in vitro." (PMID 36499440, 2022). "Although Sirt5 levels are increased in various types of cancer, how its expression is mediated in response to metabolic stress is not known." (PMID 35963851, 2022). "Sirt5 plays fundamental roles in supporting cancer cell metabolism by regulating various enzymatic activities and by protecting an enzyme essential for glutaminolysis, glutaminase C (GAC), from degradation." (PMID 35963851, 2022). "Glutaminolysis is important for the survival of cancer cells when challenged by different types of stress, and Sirt5 plays a key role in providing protection against these challenges through its ability to stabilize the cellular expression of GAC." (PMID 35963851, 2022). "SIRT5 was found to be downregulated in androgen-independent prostatecancer cells (PC-3 and PC-3M), with its expression being lower inmore advanced cancers." (PMID 35802779, 2022). "SIRT5 expression has been evaluated in various kinds of cancer, particularly in head and neck squamous cell carcinoma, endometrial carcinoma, basal carcinoma, and hepatocellular carcinoma." (PMID 36291902, 2022). "In the context of cancer, SIRT5 playsa dichotomous role, sinceit either suppresses or promotes cancer initiation or progressiondepending on various factors such as tissue or cell type and transformationstage." (PMID 35802779, 2022). "SIRT5 is an emerging cancer marker by which oncocytes can realize the reconfiguration of the metabolism for the purpose of supporting the anabolism of fast cellular fission." (PMID 35493297, 2022). "The self-assembly of peptide and formation of nanofibers in mitochondria under the catalysis of SIRT5 enhanced the fluorescent signals in cells, and therefore can be used for highly effective fluorescent imaging of cancer cells." (PMID 34425823, 2021). "SIRT5 regulates several metabolic pathways important in cancer, such as glycolysis, TCA, and urea cycle." (PMID 34650436, 2021). "Targeting sirtuins, in particular SIRT1-3 and SIRT5, is already being studied intensively in cancer research." (PMID 32917661, 2020). "The expression of SIRT4 and SIRT5 were down-regulated in cancer tissues, while SIRT6 and SIRT7 were up-regulated." (PMID 32158696, 2020). "In 72 paired KIRC tissues and corresponding adjacent normal tissues, expressions of SIRT4 and SIRT5 were down-regulated in cancer tissues than in normal tissues, while expressions of SIRT6 and SIRT7 were up-regulated in cancer tissues." (PMID 32158696, 2020). "SIRT3, SIRT4, and SIRT5 were primarily mitochondrial proteins, which have emerged as critical regulators of diverse biological events, such as cancer progression." (PMID 33282964, 2020). "The finding that the deacetylation of LDHB by SIRT5 promotes autophagy and cancer cell proliferation led us to examine K329 acetylation status in human CRC tissues." (PMID 30443978, 2019).